BCL3 (BCL3 transcription coactivator)
Diseases named in the same sentence as BCL3 in open-access papers (continued):
Sharing a sentence is not in itself a finding about the gene and the disease.
cancer (continued). "Proto-oncogene BCL3 can induce the survival and proliferation of cancer cells." (PMID 38779358, 2024). "Unsurprisingly then, when BCL3 was shown in 2019 to enhance β-catenin signaling in a panel of CRC cell lines, that suppression of BCL3 was found to reduce cancer stem cell activity within the tumour populations, as demonstrated by tumoursphere assay and stem cell markers Lgr-5 and Bmi expression." (PMID 38195591, 2024). "Additionally, Bcl-3 is involved in the development and progression of several solid types of cancer." (PMID 39327470, 2024). "Disorder of Bcl-3 may upregulate cancer cell proliferation levels by upregulating cyclin D1 and stimulating tumors to undergo G1 phase transition." (PMID 38577985, 2024). "Strategies that inhibit BCL3 therefore could lead to reduced c-Myc expression via one or more mechanisms, potentially providing a therapeutic effect in cancers where this interaction is pivotal." (PMID 38195591, 2024). "In this review we will focus on the evidence that demonstrate the direct effect of BCL3 on these oncogenic pathways, highlighting commonality in the mechanism underpinning their regulation and demonstrating the cancer modifying role that BCL3 plays in a variety of solid tumour types." (PMID 38195591, 2024). "The tumorigenic properties of Bcl-3 affect most cellular processes, including cell proliferation, cell migration and invasion, cell survival, as well as promotion of immune escape in cancer through the induction of PD-L1 expression." (PMID 39327470, 2024). "Due to the reciprocal nature of this BCL3/STAT3 axis, in cancers where both BCL3 and JAK/STAT3 signaling are upregulated, combination therapies targeting both might be beneficial." (PMID 38195591, 2024). "As BCL3 modifies multiple signaling pathways, yet is well tolerated, it has the potential to disrupt both the oncogenic drivers, and evading mechanisms inherent in cancer treatment responses." (PMID 38195591, 2024). "Since the levels of PD‐L1 and IL‐8 correlate in cancer patients, we hypothesized that the IFNγ‐induced IL‐8 expression in OC cells might be also mediated by Bcl3." (PMID 37151134, 2023). "Interestingly, nuclear BCL3 is upregulated in MCF-7 BC cells, in response to the presence of cancer-associated fibroblasts or mesenchymal stem cells via downregulation of IGFBP5 and this is important for desensitizing BC cells to fulvestrant." (PMID 35020071, 2022). "As BCL3 and PPARD are known to be associated with NF-κB and have functional roles in cell adhesion, inflammation, proliferation, and cancer progression, they could be key modulators in the pathological changes at sites of tissue injury." (PMID 35406434, 2022). "In many cancer cells, Bcl-3 exists in the form of a phosphorylated protein." (PMID 35355979, 2022). "We also explored the correlation of Bcl3 and p52 target gene expressions in cancer samples." (PMID 35990614, 2022). "It is conceivable that manipulation of Bcl-3 regulation/expression in e.g. CAR CD8+ T cells might allow for improved anti-cancer activities of these cells." (PMID 33508001, 2021). "Due to the overactivation of Bcl-3 and β-catenin that occurs in many cancers, we hypothesize that there is a potential functional relationship between these two transcriptional regulators." (PMID 32355204, 2020). "In conclusion, BCL-3 may represent an exciting new route for targeting the Hallmarks of Cancer; in particular by limiting the impact of the enabling hallmarks of tumour promoting inflammation and cell plasticity." (PMID 31930327, 2020). "BCL3 is a well established factor for maintaining cancer cell proliferation, ant-apoptosis and survival, might explain its relation to disease prognosis." (PMID 30357752, 2019). "Whether serum Bcl-3 protein levels in the patients with cancers are increased needs to be further investigated." (PMID 29228604, 2017). "Another oncogenic property of Bcl-3 is the ability to promote cell survival in cancer cells." (PMID 25929479, 2015).
cancer (continued). "In the present study, we investigated whether localization of Bcl-3 in cancer cells follows the same pattern as in previously reported solid tumours." (PMID 25929479, 2015). "Protein Bcl-3, the expression of which is upregulated in both cancer cell lines, may bind to NFKB1 and NFKB2 homodimers and form complexes that function as transcriptional activators." (PMID 24037645, 2013). "Bcl-3 may be needed to overcome the deleterious effect of DNA damage on cancer cells with aberrant mitosis, and the importance of Bcl-3 could be exploited for the development of selective inhibitors of tumorigenesis." (PMID 20731879, 2010). "Thus the basal regulation of cancer cell survival appears to be dependent upon the opposing functions of JNK2/Bcl-3 (pro-survival) and JNK1/c-Jun (pro-apoptotic) and to be under constitutive control by JNK2." (PMID 19806201, 2009). "These cancer-related differences may reflect differences in sub-cellular localisations of pro- and anti-apoptotic proteins such as c-Jun and Bcl-3 in cancer versus non-cancer cells (see Results)." (PMID 19806201, 2009). "BCL3 has also been suggested to be a key determinant in the COX-2-mediated response to inflammatory cytokines in colorectal tumour cells, promoting PGE2-driven tumorigenesis – a pathway known to be involved in several hallmarks of cancer and associated with WNT signaling." (PMID 38195591, 2024). "Thus, the combined overexpression of BCL3 and c-Myc in certain cancers may lead to a synergistic oncogenic effect." (PMID 38195591, 2024). "By binding to other NFκB proteins, Bcl3 regulates transcription of many NFκB-dependent genes, including genes involved in the regulation of the cell cycle, survival, proliferation, migration, chemotherapy resistance and cancer stemness, as well as pro- and anti-inflammatory genes." (PMID 39123403, 2024). "BCL3 on the other hand was originally identified as a non-canonical regulator of NF-kB transcription factor pathways – a signaling mechanism associated with important cell outcomes including many of the hallmarks of cancer." (PMID 38195591, 2024). "Previous studies have found that BCL3 could be involved in immune response in various cancer types." (PMID 35488886, 2022). "Consequently, BCL3 was found in cancer cells in the cyctosol as well as in the nucleus." (PMID 35020071, 2022). "Although most studies have shown that BCL3 promotes cell survival and proliferation of different cell types for its role as a key regulator of NF-κB signaling, recent works have shown that BCL3 contribution to cancer goes beyond this role in these two cancer hallmarks." (PMID 34422669, 2021). "Since it has been shown that Bcl-3 is heavily phosphorylated and this phosphorylation modulates its activity, it remains an open question whereas lower Bcl-3 levels of a specific phosphoisoform could be also acting in cancer progression." (PMID 22195643, 2011). "Notably, SP1-enriched promoters were predominantly associated with known oncogenes, including Ahcyl2, Bcl3, and Sp1 itself, suggesting that SP1’s oncogenic potential may arise from its role in regulating transcription of cancer-associated genes." (PMID 40884402, 2025). "Among the genes listed in the COSMIC50 database for cancer, seven blood lifespan cis-eGenes (ALDH2, BCL3, CDKN2A, FES, HIST1H3B, SH2B3, and SMARCA4) were identified (fold enrichment = 1.4, P = 0.22, hypergeometric test)." (PMID 32358504, 2020). "We also thank Alain Chariot (University of Liège, Belgium) for the gift of the BCL-3 ANK M123 mutant and the Cancer Research UK Colorectal Tumour Biology Group for useful discussion." (PMID 26033966, 2016). "Our results demonstrate that HCT116 cancer cells are primed to undergo basal apoptosis in response to (i) JNK2 depletion, (ii) Bcl-3 depletion or (iii) exogenous over-expression of c-Jun." (PMID 19806201, 2009). "We also found that N4BP2 and Bcl-3 are expressed in all NPC cell lines examined and were higher for certain cancers." (PMID 17626640, 2007).
cancer (continued). "Some researchers also suggest that microbial-related metabolites, such as propionate, butyrate, PYY, and Bcl3, could be useful for PDAC diagnosis and classification, although the cancer-specific nature of these changes has yet to be fully elucidated." (PMID 40102723, 2025). "Connections: This pattern suggests that BCL3 and PTK7 may enhance cancer progression under varying deuterium levels, potentially complicating the anti-cancer effects of DDW." (PMID 41303451, 2025). "The likelihood that BCL3 plays a more universal role in regulating cancer cell stemness in other tumour types is supported by the evidence that BCL3 is also permissive for stemness in the non-tumour setting." (PMID 38195591, 2024). "In concordance, Pim3, Bcl3 and Inhbb were upregulated in lung ECs 14 d, but not 7d after cancer cell inoculation." (PMID 39627185, 2024). "In addition, we predicted the sensitivity of common anti-cancer drugs on prognostic signature, including CCR5, HMOX1, CTSC, CD5, BCL3, CDH1, TYROBP and CD38." (PMID 38767825, 2024). "Although Bcl-3 is a well-known proto-oncogene and is dysregulated in many types of cancer, thus far, no therapeutic agents have been developed targeting Bcl-3 to regulate its effects." (PMID 38238702, 2024). "BCL3 has been recognized for some time to be a direct transcriptional target of STAT3 in a cancer context yet the reciprocal relationship was not described until relatively recently." (PMID 38195591, 2024). "It is worth noting however that a reciprocal relationship may also exist in some cancer cell types, as p-SMAD3 has been shown to bind to the BCL3 promoter, upregulating BCL3 in response to TGF-β." (PMID 38195591, 2024). "The ROC analysis showed that Bcl3 gene possessed highest specificity and sensitivity to distinguish cancer and control samples while other identified genes failed to correlate with that." (PMID 35388653, 2022). "BCL3 activated STAT3, an aggressive oncogene in human cancer and promoted metastasis." (PMID 35399006, 2022). "Moreover, Bcl-3 can induce the STAT3 gene in human cancer cells, while STAT3 can reciprocally induce Bcl-3 expression in mammary epithelial cells." (PMID 35681213, 2022). "Our results provide new insight into the molecular regulation of CD8+ T cell effector response and memory cell generation, establishing Bcl-3 and its pathways as a target to optimize CD8+ T cell effector responses to various immunogens including infectious agents, cancer cells, and vaccines." (PMID 33508001, 2021). "NF-κB signalling is recognized to have contrasting function depending on the biological context, consistent with the role of BCL-3 in cancer compared with its role in non-malignant, inflammatory models." (PMID 31930327, 2020). "In the cancer tissues or cells Bcl-3 was localized in the cytoplasm, while non-cancerous tissue/cells showed an accumulation of Bcl-3 in the nuclei." (PMID 25929479, 2015). "Surprisingly, we found that in freshly isolated colon biopsies Bcl-3 was localized in the cytoplasm of the cancer tissues, while non-cancerous tissue showed an accumulation of Bcl-3 in the nuclei." (PMID 25929479, 2015). "We found that Bcl-3 is mainly localized in the cytoplasm in cancer tissues while nuclear localization of Bcl-3 was detected in non-cancerous tissue." (PMID 25929479, 2015). "In addition, the five genes (JUN, PRKACA, SMAD2, ESR1, and BCL3) shared by the OV and multi-NCA biomarkers form a small network module and are recognized as cancer-related genes." (PMID 26202601, 2015). "Since Bcl-3 knockout mice do not show any gross defect in DNA damage response, the participation of this oncogene should be specific to cancer cells and probably requires de novo overexpression." (PMID 20731879, 2010). "In many cancers, Bcl3 levels are 3–4-fold higher than non-cancerous tissues or cells." (PMID 35990614, 2022).
cancer (continued). "For instance, Sox2 and Bcl-3 cooperate to maintain stemness of embryonal stem cells, STAT3 can convert non-CSCs to CSCs, AKT is involved in maintaining Sox2-dependent cervical CSC activity and CSCs isolated from ERα-positive cancer show a hyperactive PI3K pathway." (PMID 33228022, 2020). "As BCL-3 has been reported to promote the stem-like potential of cancer cells, we suggest that targeting BCL-3 could increase the tumour response to conventional treatment, reduce the chance of relapse and hence improve the prognosis for cancer patients." (PMID 31930327, 2020). "Due to its role in regulating both β-catenin and NF-κB signalling, it is interesting to speculate that BCL-3 may enhance the de-differentiation of non-stem cells, therefore aiding reconstitution of the tumour when the cancer stem cells have been deleted." (PMID 31930327, 2020). "Interestingly, following activity onset (CT38), pathways established to be involved in cancer-induced muscle wasting, including JAK-STAT, tumor necrosis factor (TNF), and FoxO signaling pathways, were enriched from genes increased in KPC mice (e.g., Jak3, Osmr, Nfkbia, Bcl3, Gadd45g, and Cebpb)." (PMID 40349340, 2025). "Despite these data showing the role of BCL-3 as both a pro-inflammatory and an anti-inflammatory mediator in non-cancer tissue, it does still appear that BCL-3 has similar control over regulation of apoptosis in non-malignant tissue compared with the role of BCL-3 in cancers." (PMID 31930327, 2020).
tumor (78 papers, 2007 to 2026). "Our findings show for the first time that loss of Bcl3 in tumour cells can induce senescence and upregulate the accompanying SASP cytokines that are a hallmark of senescence." (PMID 38255248, 2024). "Instead, a significant decrease in cell turnover was observed at the metastatic sites, suggesting that primary tumour growth was less affected by BCL3 loss than at distal lesions." (PMID 38195591, 2024). "Bcl3 expression is elevated in a variety of tumors and is associated with tumor development and metastasis and is closely related to inflammatory diseases." (PMID 34530917, 2021). "Strong nuclear BCL-3 staining was also reported in 33% of 270 tumour samples, and was suggested to be an important diagnostic determinant." (PMID 31930327, 2020). "Weobserved increased primary tumor volumes but significantly reduced numbersof lung metastatic foci in Bcl-3-deficient MMTV-PyMT mice." (PMID 27906182, 2016). "One of these targets might be BCL3, a recognized oncogene for hematological malignancies, whose alterations have been associated with tumor progression and poor prognosis." (PMID 34422669, 2021). "Further studies with functional approaches are needed to describe the precise immune response-modifying processes of BCL3 in the tumour microenvironment, based on gene expression levels." (PMID 40486320, 2025). "The inhibition of the pro-apoptotic proteins BAX and BAD by elevated BCL3 expression leads to tumour cell survival and suppressed cytotoxic immune responses." (PMID 40486320, 2025). "Upregulation of Junb and Bcl3 induces the expression of NF-κB-dependent proinflammatory cytokines, thereby inhibiting tumor growth." (PMID 39796281, 2025). "Bcl3 has been identified as a candidate proto-oncogene, while accumulating evidence suggests its potential tumor-suppressive functions." (PMID 40427768, 2025). "The elevated expression of BCL3 is highly correlated with the advanced stage of the tumour, reduced immune infiltration, and multi-modal treatment requirements." (PMID 40486320, 2025). "Patients with tumours exhibiting elevated BCL3 expression levels require additional treatments, such as chemotherapy in combination with radiotherapy or targeted molecular drugs, to overcome treatment resistance and improve survival rates." (PMID 40486320, 2025). "BCL3 functions as an oncogene, enabling immune evasion and creating an immunosuppressive microenvironment that leads to tumour cell survival along with treatment resistance." (PMID 40486320, 2025). "Research findings establish an important connection between BCL3 overexpression and suppressive immune activity occurring within tumour environments." (PMID 40486320, 2025). "Bcl-3 was also shown to induce the expression of the immune checkpoint PD-L1 expression in tumor cells." (PMID 38238702, 2024). "Common changes in differently expressed genes resulted in a significant downregulation of tumor-promoting genes (BCL3, NR6A1, and PFKFB3)." (PMID 38779358, 2024). "IHC was used to examine BCL-3 abundance in the nuclei of tumor cells and staining scored on a 4-point scale that was converted to a binary grade (high or low)." (PMID 38420615, 2024). "In this study, we identify Bcl3/NF-κB dependence in ER-positive breast cancer cell lines and demonstrate the importance of Bcl3 in maintaining tumour cell survival." (PMID 38255248, 2024). "Together with the potential suppression of PD-L1, this raises the possibility of a dual effector role for BCL3 inhibition in an appropriate tumour microenvironment." (PMID 38195591, 2024). "BCL3 meets the requirements of a therapeutic target that addresses both primary tumour growth and metastasis." (PMID 38195591, 2024). "The JAK-STAT pathway is known to regulate metastasis and tumor angiogenesis, and interestingly, two prominent rCap markers Pim3 and Bcl3 are direct transcriptional targets of the JAK-STAT pathway." (PMID 39627185, 2024).